TAFAZZIN (tafazzin, phospholipid-lysophospholipid transacylase)
Description:
Acyltransferase required to remodel newly synthesized phospholipid cardiolipin (1',3'-bis-[1,2-diacyl-sn-glycero-3-phospho]- glycerol or CL), a key component of the mitochondrial inner membrane, with tissue specific acyl chains necessary for adequate mitochondrial function. Its role in cellular physiology is to improve mitochondrial performance. CL is critical for the coassembly of lipids and proteins in mitochondrial membranes, for instance, remodeling of the acyl groups of CL in the mitochondrial inner membrane affects the assembly and stability of respiratory chain complex IV and its supercomplex forms (By similarity). Catalyzes the transacylation between phospholipids and lysophospholipids, with the highest rate being between phosphatidylcholine (1,2-diacyl-sn-glycero-3-phosphocholine or PC) and CL. Catalyzes both 1-acyl-sn-glycero-3-phosphocholine (lysophosphatidylcholine or LPC) reacylation and PC-CL transacylation, that means, it exchanges acyl groups between CL and PC by a combination of forward and reverse transacylations. Also catalyzes transacylations between other phospholipids such as phosphatidylethanolamine (1,2-diacyl-sn-glycero-3-phosphoethanolamine or PE) and CL, between PC and PE, and between PC and phosphatidate (1,2-diacyl-sn-glycero-3-phosphate or PA), although at lower rate. Not regiospecific, it transfers acyl groups into any of the sn-1 and sn-2 positions of the monolysocardiolipin (MLCL), which is an important prerequisite for uniformity and symmetry in CL acyl distribution. Cannot transacylate dilysocardiolipin (DLCL), thus, the role of MLCL is limited to that of an acyl acceptor. CoA-independent, it can reshuffle molecular species within a single phospholipid class. Redistributes fatty acids between MLCL, CL, and other lipids, which prolongs the half-life of CL. Its action is completely reversible, which allows for cyclic changes, such as fission and fusion or bending and flattening of the membrane. Hence, by contributing to the flexibility of the lipid composition, it plays an important role in the dynamics of mitochondria membranes. Essential for the final stage of spermatogenesis, spermatid individualization (By similarity). Required for the initiation of mitophagy. Required to ensure progression of spermatocytes through meiosis (By similarity). Exon 7 of human tafazzin is essential for catalysis. [Isoform 1]: Catalyzes the transacylation between lysophosphatidate (such as 1-acyl-sn-glycero-3-phosphate) and phosphatidylglycerol (1,2-diacyl-sn-glycero-3-phospho-(1'-sn-glycerol)). Contributes to cardiolipin (1',3'-bis-[1,2-diacyl-sn-glycero-3-phospho]-glycerol or CL) remodeling. [Isoform 3]: Catalyzes the transacylation between lysophospholipids and phospholipids, and plays a fundamental role in cardiolipin (1',3'-bis-[1,2-diacyl-sn-glycero-3-phospho]-glycerol or CL) metabolism and remodeling. [Isoform 5]: Catalytically inactive. [Isoform 7]: Catalytically inactive.
Synonyms: Taz; EFE2; G4.5; BTHS; TAZ1; CMD3A; EFE; LVNCX
Tractability: Antibody: UniProt places it where antibodies can reach, with high confidence. PROTAC: ubiquitination databases record sites on it.
Target class: Enzyme; Transferase
Gene: Protein-coding gene on chromosome X (154,409,456 to 154,421,726, forward strand). Ensembl gene ENSG00000102125.
Subcellular location: Mitochondrion outer membrane; Mitochondrion inner membrane; Mitochondrion membrane (Isoform 1); Cytoplasm (Isoform 2); Mitochondrion membrane (Isoform 3); Mitochondrion membrane (Isoform 5); Cytoplasm (Isoform 6); Mitochondrion membrane (Isoform 7); Cytoplasm (Isoform 8); Cytoplasm (Isoform 9)
Pathways (Reactome):
Metabolism: Acyl chain remodeling of CL
Protein localization: Mitochondrial protein import
Gene Ontology:
Molecular function: 1-acylglycerophosphocholine O-acyltransferase activity; 1-acylglycerol-3-phosphate O-acyltransferase activity; acyltransferase activity, transferring groups other than amino-acyl groups; acyltransferase activity
Biological process: cardiolipin acyl-chain remodeling; cristae formation; inner mitochondrial membrane organization; phospholipid metabolic process; positive regulation of ATP biosynthetic process; positive regulation of cardiolipin metabolic process
Cellular component: mitochondrial intermembrane space; mitochondrial membrane; mitochondrion; mitochondrial inner membrane; cytoplasm; mitochondrial outer membrane
Gene-disease validity (ClinGen):
ClinGen rates the evidence that TAFAZZIN causes each of these diseases.
Barth syndrome (X-linked): Definitive. Barth syndrome (BTHS) is an inborn error of phospholipid metabolism characterized by dilated cardiomyopathy (DCM), skeletal myopathy, neutropenia, growth delay and organic aciduria.
Homologues: Orthologues: macaque TAFAZZIN (98% identical), chimpanzee TAFAZZIN (89% identical), mouse Tafazzin (87% identical), rabbit TAFAZZIN (87% identical), rat Tafazzin (87% identical), guinea pig TAFAZZIN (84% identical), pig TAFAZZIN (66% identical), dog TAZ (66% identical), tropical clawed frog tafazzin (62% identical), zebrafish tafazzin (59% identical), Drosophila melanogaster Taz (40% identical), Caenorhabditis elegans acl-3 (39% identical).
Diseases named in the same sentence as TAFAZZIN in open-access papers:
TAFAZZIN is named in the same sentence as 25 diseases in open-access papers, as found by Europe PMC text mining. Sharing a sentence is not in itself a finding about the gene and the disease. The quoted sentences say what the papers report.
Barth syndrome (40 papers, 2019 to 2026). "Barth Syndrome (BTHS) is a debilitating X-linked genetic disorder caused by mutations in the gene encoding TAFAZZIN, an enzyme responsible for the remodeling of cardiolipin." (PMID 41823370, 2026). "Barth syndrome (BTHS) is a life-threatening genetic disorder caused by a mutation in the TAFAZZIN gene (TAZ), encoding a transacylase involved in the remodeling of the mitochondrial phospholipid-cardiolipin (CL)." (PMID 40491447, 2025). "Several genes have been implicated in LVNC, including those responsible for encoding sarcomeric proteins (TTN and MYH7), cytoskeletal proteins (P121L), genes related to nuclear membrane components, chaperones, and the TAFAZZIN gene, causing Barth syndrome." (PMID 40004439, 2025). "Barth syndrome (BTHS) is a rare X‐linked recessive disorder characterized by mutations in the TAFAZZIN gene, leading to mitochondrial dysfunction, cardioskeletal myopathy, neutropenia, exercise intolerance, and growth delay." (PMID 40626056, 2025). "Barth syndrome (BTHS) is a rare X-linked recessively inherited disorder caused by variants in the TAFAZZIN gene, leading to impaired conversion of monolysocardiolipin (MLCL) into mature cardiolipin (CL)." (PMID 41083823, 2025). "Mutations in TAFAZZIN can cause Barth’s Syndrome, which is characterised by cardiomyopathy, skeletal myopathy and impaired growth." (PMID 41345286, 2025). "Barth syndrome (MIM: 302060) is a rare X-linked recessively inherited mitochondrial disorder caused by pathogenic variants in TAFAZZIN." (PMID 41083823, 2025). "For instance, a mutation in TAFAZZIN, which is a gene encoding taz protein associated with x-linked Barth syndrome, was first predicted to be synonymous (NM_000116.3: p.Gly116Gly) and was therefore excluded from the WES analysis." (PMID 39323625, 2024). "A notable example is Barth syndrome, an X-linked inherited disorder caused by mutations in the TAFAZZIN gene encoding a mitochondrial transacylase involved in the biogenesis of cardiolipin (a mitochondrial-specific phospholipid)." (PMID 39594199, 2024). "Disruption of CL metabolism, caused by mutations in the CL remodeling enzyme TAFAZZIN, results in the life-threatening disorder Barth syndrome (BTHS)." (PMID 38301889, 2024). "As TAFAZZIN is mutated in Barth syndrome, an X-linked cardio- and skeletal myopathy, this implicates potential defects in ANT assembly and function in this disease." (PMID 38839991, 2024). "Barth Syndrome (BTHS) is a rare X-linked genetic disease caused by a mutation in the TAFAZZIN gene, which codes for the protein tafazzin involved in cardiolipin remodeling." (PMID 37237543, 2023). "Mutations in the CL remodeling enzyme TAFAZZIN cause Barth syndrome, a life-threatening genetic disorder that results in severe physiological defects, including cardiomyopathy, skeletal myopathy, and neutropenia." (PMID 36739949, 2023). "Barth Syndrome (BTHS) is a rare X-linked mitochondrial disorder due to mutations in the gene TAFAZZIN, which leads to immature cardiolipin (CL) remodeling and is characterized by the development of cardiomyopathy." (PMID 36035919, 2022). "When the remodeling process of CL is disturbed by TAFAZZIN mutations, the structural changes to the mitochondrial membrane cause reduced mitochondrial function and Barth syndrome." (PMID 36107830, 2022). "Barth syndrome (BTHS) is a rare genetic disorder due to mutations in the TAFAZZIN gene, leading to impaired maturation of cardiolipin and thereby adversely affecting mitochondrial function and energy metabolism, often resulting in cardiomyopathy." (PMID 36211560, 2022). "Another condition linking fat oxidation with LA-enriched CL is the cardio-skeletal myopathy Barth syndrome, caused by loss of the CL-remodeling enzyme tafazzin, encoded by the TAFAZZIN gene." (PMID 36671725, 2022). "Barth syndrome (BTHS) is a rare genetic disease caused by mutations in the TAFAZZIN gene." (PMID 39962231, 2025).
Barth syndrome (continued). "Barth Syndrome is a rare, X-linked disorder caused by mutation of the gene TAFAZZIN (TAZ)." (PMID 37756350, 2023). "Prominent examples of genetically caused MCM include the Barth syndrome, caused by a mutation in the TAFAZZIN (TAZ) gene, Friedreich’s ataxia, caused by a mutation in the FRATAXIN(FXN) gene and propionic acidemia, caused by a mutation in the enzyme propionyl-CoA carboxylase." (PMID 39086669, 2023). "However, when TAFAZZIN is mutated, CL remodeling is impeded, leading to mitochondrial dysfunction and the disease Barth syndrome." (PMID 36107830, 2022). "Barth syndrome (BTHS) is a rare X-linked genetic disorder that primarily affects males, resulting from a mutation in the TAFAZZIN gene (TAZ, G4.5) located on chromosome Xq28." (PMID 40075507, 2025). "Barth syndrome (BTHS; Online Mendelian Inheritance in Man #302060) is an X-linked inherited disorder due to mutations in TAFAZZIN." (PMID 40313767, 2025). "Barth syndrome (BTHS) is an ultra-rare genetic disease caused by a mutation in the TAFAZZIN gene, located on the X chromosome." (PMID 40901530, 2025). "Barth syndrome (BTHS) is a rare X-linked genetic disease in which mitochondrial oxidative phosphorylation is impaired due to a mutation in the TAFAZZIN gene." (PMID 39372601, 2024). "Barth syndrome (BTHS) is a rare genetic disorder caused by mutations in the TAFAZZIN gene, which encodes a transacylase responsible for remodeling the vital mitochondrial lipid cardiolipin." (PMID 38769106, 2024). "Barth syndrome (BTHS) is an X-linked mitochondrial lipid disorder caused by mutations in the TAFAZZIN (TAZ) gene, which encodes a mitochondrial acyltransferase/transacylase required for cardiolipin (CL) biosynthesis." (PMID 35456462, 2022). "Barth syndrome (BTHS) is an ultrarare, infantile-onset, X-linked recessive mitochondrial disorder that primarily affects males, owing to mutations in TAFAZZIN, which catalyzes the remodeling of cardiolipin, a mitochondrial phospholipid required for oxidative phosphorylation." (PMID 40555742, 2025). "Barth syndrome (BTHS) is a rare, X-linked disorder that stems from mutations in the TAFAZZIN (TAZ) gene with varying disease severity among patients." (PMID 40281531, 2025). "Barth Syndrome (BTHS) is an early onset, lethal X-linked disorder caused by a mutation in tafazzin (TAFAZZIN), a mitochondrial acyltransferase that remodels monolysocardiolipin (MLCL) to mature cardiolipin (CL) and is essential for normal mitochondrial, cardiac, and skeletal muscle function." (PMID 39769321, 2024). "Barth syndrome (BTHS) is a rare disorder caused by mutations in the TAFAZZIN gene." (PMID 38769106, 2024). "The importance of the CL remodeling pathway is underscored by the life-threatening disease Barth syndrome (BTHS), in which patients bear mutations in TAFAZZIN, the transacylase responsible for adding polyunsaturated fatty acid chains to monolyso-CL (MLCL)." (PMID 38301889, 2024). "Variations in TAFAZZIN lead to the life-threatening disease Barth syndrome (BTHS), underscoring the importance of CL homeostasis and remodeling for cellular and organismal fitness." (PMID 35693555, 2022). "Barth syndrome (BTHS, OMIM 302060) is a genetic disorder caused by variants of the TAFAZZIN gene (G 4.5, OMIM 300394)." (PMID 35693555, 2022). "Barth Syndrome (BTHS), a genetic disease associated with early-onset cardioskeletal myopathy, is caused by loss-of-function mutations of the TAFAZZIN gene, which is responsible for remodeling the mitochondrial phospholipid cardiolipin (CL)." (PMID 36400945, 2022). "Barth syndrome (BTHS; Mendelian Inheritance in Man accession number: 302060) is a rare X-linked inborn error of mitochondrial phospholipid metabolism caused by pathogenic variants in the gene TAFAZZIN." (PMID 34314685, 2021). "Barth syndrome (BTHS) is a rare, X-linked genetic disorder caused by mutations in the TAFAZZIN (also known as G4.5, formerly annotated as TAZ) gene on chromosome Xq28." (PMID 35456462, 2022).
cardiomyopathy (9 papers, 2019 to 2025). A disease of the heart muscle or myocardium proper. "Barth syndrome (BTHS) is an X-linked mitochondrial disease characterized by fatigue, skeletal muscle weakness, cardiomyopathy, neutropenia, and growth delay due to inherited TAFAZZIN enzyme mutations." (PMID 40161853, 2025). "BTHS is generally characterized by skeletal myopathy, cardiomyopathy, neutropenia, fatigue, and short stature due to inherited TAFAZZIN (TAZ) mutations." (PMID 39728085, 2024). "Barth syndrome (BTHS) is an X-linked recessive genetic disorder resulting from mutations in the gene encoding Tafazzin (TAFAZZIN) with individuals presenting with cardiomyopathy, skeletal myopathy, muscle weakness, exercise intolerance, neutropenia, and growth delays." (PMID 37651450, 2023).
neutropenia (8 papers, 2016 to 2025). A decrease in the number of neutrophils found in the blood. "Overall, our findings demonstrate that mitochondrial dysfunction secondary to TAFAZZIN loss of enzymatic function underlies BTHS-associated neutropenia and lymphopenia." (PMID 40762880, 2025).
Skeletal myopathy (8 papers, 2019 to 2025). "Therefore, decreased MyoD1 in TAFAZZIN-deficient myoblasts may serve as the mechanism underlying the development of skeletal myopathy in BTHS patients." (PMID 36739949, 2023).
primary cardiomyopathy (1 paper, 2024). "As TAFAZZIN gene was not included in the core genes for primary cardiomyopathy, the gene prioritization was put at a lower position and the variant change had probably been filtered out." (PMID 38586174, 2024).
genetic disease (10 papers, 2019 to 2025). "Barth syndrome (BTHS) is an X-linked recessive genetic disorder due to mutations in the Tafazzin (TAFAZZIN) gene that lead to cardiac and skeletal muscle mitochondrial dysfunction." (PMID 37651450, 2023).
TAFAZZIN also shares sentences with these, for which no sentence is quoted: mitochondrial disease (4 papers); Hypoglycemia (2); lactic acidosis (2); Arrhythmia (1); Ataxia (1); bone marrow disease (1); Brugada syndrome (1); cardiac amyloidosis (1); cardiac sarcoidosis (1); congestive heart failure (1); diabetes (1); Hyperammonemia (1); hyperglycerolemia (1); Infertility (1); Lowe syndrome (1); lymphopenia (1); male infertility (1); Rett syndrome (1); Transthyretin amyloidosis (1).